BMAL1 (basic helix-loop-helix ARNT like 1)
Diseases named in the same sentence as BMAL1 in open-access papers (continued):
Sharing a sentence is not in itself a finding about the gene and the disease.
renal fibrosis (5 papers, 2021 to 2026). A final common manifestation of a wide variety of chronic kidney diseases characterized by glomerulosclerosis and tubulointerstitial fibrosis. "In contrast, its role in chronic kidney disease is more complex, as Bmal1 knockout leads to different outcomes for renal fibrosis depending on the specific model." (PMID 39858471, 2025). "However, their findings indicated that knocking out the renal Bmal1 gene had negligible effects on renal fibrosis." (PMID 39858471, 2025). "The circadian rhythm gene Bmal1 plays a significant role in the regulation of renal fibrosis." (PMID 39858471, 2025). "However, our own recent study found that postnatal Bmal1 deletion in mice protected against renal fibrosis via suppressing Gli2 transcription, which provides a prominent role of the core clock gene Bmal1 in tubulointerstitial fibrosis." (PMID 34207942, 2021). "For instance, Chen W. and Zhang J. found that Bmal1 alleviates renal fibrosis in UUO mouse models; in contrast, Rey-Serra C. observed no significant improvement in fibrosis following the knockout of Bmal1 in the kidneys." (PMID 39858471, 2025).
alcoholic liver diseases (4 papers, 2021 to 2023). A disorder caused by damage to the liver parenchyma due to alcohol consumption. "Further studies showed that the alleviation of alcoholic liver disease (ALD) by Bmal1 was associated with glycolytic pathway suppression and M1 macrophage polarization." (PMID 33790796, 2021). "It is noteworthy that the BMAL1 protein plays an important role in the protection of hepatocytes in alcoholic liver disease." (PMID 36142658, 2022). "Brain and Muscle ARNT-Like 1 (BMAL1), which is a core clock gene, was found to be involved in the regulation of hepatic lipogenesis, and its overexpression was found to be protective against alcoholic liver damage in mice, supporting hepatoprotective effects of a robust circadian clock." (PMID 37987396, 2023).
cardiac hypertrophy (4 papers, 2022 to 2024). "ARNTL (BMAL1) has been linked to cardiac hypertrophy in previous publications." (PMID 38799057, 2024). "Furthermore, gain- and loss-of-function studies revealed that BMAL1 has an effect on Ang II-induced cardiac hypertrophy." (PMID 35996077, 2022). "Our results showed that overexpression of BMAL1 effectively resisted cardiac hypertrophy induced by Ang II." (PMID 35996077, 2022). "We found that Ang II-induced cardiac hypertrophy as a result BMAL1 expression was reduced." (PMID 35996077, 2022). "In the present study, we identified a potential link between BMAL1 and cardiac hypertrophy." (PMID 35996077, 2022). "To explore this gene further, we examined Bmal1 ChIP-seq data from the heart, kidney, and liver along with ATAC-seq data from mouse hearts subjected to transverse aortic constriction-induced cardiac hypertrophy." (PMID 38830405, 2024).
Cerebral ischemia (4 papers, 2022 to 2025). Restriction of arterial blood supply to the brain associated with insufficient oxygenation to support the metabolic requirements of the tissue. "The circadian clock gene brain and muscle Arnt-like 1 (Bmal1) plays a crucial role in cerebral ischemia-reperfusion injury." (PMID 40527853, 2025). "SR9009 may have an effect on the expression of Bmal1 and Clock gene and protein in cerebral ischemia mice independent of Rev-erbα." (PMID 37063298, 2023).
COVID-19 (4 papers, 2022 to 2025). A disease caused by infection with severe acute respiratory syndrome coronavirus 2. "All this suggests clock genes, especially BMAL1, as a strong candidate in the pathogenesis of the possible COVID-19-induced acceleration of aging, with a potential role for iron disruption and ferroptosis." (PMID 38641847, 2024). "BMAL1/ARNTL deficiency triggers the production of pro-inflammatory cytokines, which could pave the way for further consideration of BMAL1/ARNTL in the extended pathogenesis of COVID-19." (PMID 38641847, 2024). "This alludes to the hypothesis that COVID-19-mediated dysfunctional activity and degradation of BMAL1/ARNTL can mediate chronic microglial-inflammatory responses and neuronal ferroptosis-mediated demise." (PMID 38641847, 2024). "Moreover, variation in CLOCK and BMAL1/ARNTL expression in monocytes impacts cytokine production, showing the effect clock genes could have on COVID-19 progression." (PMID 38641847, 2024).
endotoxemia (4 papers, 2022 to 2025). "Our in vivo results suggested that the circadian of Bmal-1 and its downstream Akt/Nrf2 pathway in rat heart were inhibited under endotoxemia condition." (PMID 39296207, 2024). "The knock-out of myeloid cell's Bmal-1 can disrupt the circadian rhythm and decrease the survival rate in cases of LPS-induced endotoxemia." (PMID 39296207, 2024). "The number of neutrophils exhibits lung-specific diurnal variation with larger amplitude, which remains rhythmic also during endotoxemia, but the mobilization and circadian pattern disappeared in Bmal1-deleted lungs." (PMID 35281442, 2022). "During the two days from the onset of endotoxemia at the late resting phase to death, the circadian expression rhythm of the Bmal1 gene becomes arrhythmic and remains at a high level in the lung, while that of the Rev-erbα gene shows a distorted but rhythmic pattern compared to healthy lungs." (PMID 35281442, 2022). "Totally, these results indicated that the circadian of Bmal-1 and its downstream AKT/Nrf2 pathway in rat heart were inhibited under endotoxemia condition." (PMID 39296207, 2024).
experimental autoimmune encephalomyelitis (4 papers, 2017 to 2025). An autoimmune demyelinating disease of the central nervous system that is produced experimentally in animals by the injection of homogenized brain or spinal cord in Freund's adjuvant. "We previously demonstrated that myeloid BMAL1 protects against lipopolysaccharide (LPS) induced lethality, and that BMAL1 maintains an anti-inflammatory environment during experimental autoimmune encephalomyelitis (EAE), a mouse CNS autoimmune disease model." (PMID 34858390, 2021). "There are conflicting reports on the expression of Bmal1 in T cells and function of Bmal1 in the development of experimental autoimmune encephalomyelitis (EAE), a murine model for MS." (PMID 29234010, 2017). "Here we show that BMAL1 and time-of-day regulate the accumulation and activation of various immune cells in a CNS autoimmune disease model, experimental autoimmune encephalomyelitis (EAE)." (PMID 29234010, 2017).
Impaired glucose tolerance (4 papers, 2017 to 2023). An abnormal resistance to glucose, i.e., a reduction in the ability to maintain glucose levels in the blood stream within normal limits following oral or intravenous administration of glucose. "Remarkably, a pancreas-specific Bmal1 knockout results in elevated glucose levels, impaired glucose tolerance, and decreased insulin secretion already at a very young (2–4 months) age." (PMID 33683376, 2021). "Moreover, a ß-cell-specific Bmal1 knockout results in hyperglycemia and impaired glucose tolerance." (PMID 33683376, 2021).
influenza infection (4 papers, 2019 to 2023). "The protein BMAL1 plays a pivotal role in alveolar epithelial cells (AECs), with specific BMAL1 deletion disrupting lung neutrophil infiltration, biomechanical functions, and the response to influenza infection." (PMID 38067152, 2023). "Involvement of BMAL1 in the regulation of neutrophil infiltration and course of influenza infection has been demonstrated lately in knockout animal and cell models." (PMID 35763527, 2022). "To confirm that the time of day difference in mortality and morbidity from influenza infection was secondary to circadian rhythms, we genetically disrupted the molecular clock by deleting Bmal1 and infected these mice with IAV." (PMID 31511530, 2019).
liver disease (4 papers, 2021 to 2024). "For example, a recent study shows that disruption of the clock gene BMAL1 impacts insulin sensitivity and liver disease." (PMID 36321857, 2022). "However, Bmal1 was not critical for the inflammatory instauration associated to lung and liver disease, and in this study, the expression of cytokines and inflammatory markers was not affected in the global Bmal KO after UUO." (PMID 37487638, 2023).
myocardial ischemia (4 papers, 2014 to 2025). A disorder of cardiac function caused by insufficient blood flow to the muscle tissue of the heart. "Bmal1 knockdown led to changes in transcriptional levels of genes associated with neural activity, thereby preventing ventricular arrhythmias after myocardial ischemia." (PMID 36247430, 2022). "Interestingly, Bmal1 knockdown in the left stellate ganglion leads to changes in the transcriptional levels of genes associated with neural activity, thereby preventing ventricular arrhythmias after myocardial ischemia." (PMID 37189459, 2023). "In the pathological state of myocardial ischemia, BMAL1 ameliorates myocardial ischemic injury by regulating intrinsic mechanisms such as oxidative stress response, energy metabolism, immune-inflammatory response, and apoptosis and autophagy in cardiomyocytes." (PMID 40429770, 2025). "BMAL1 regulates ATP production by affecting mitochondrial function, which, in turn, affects the development of myocardial ischemia." (PMID 40429770, 2025). "Gene-level studies have revealed an alteration in BMAL1 at the gene level in the pathological state of myocardial ischemia, providing new ideas for the in-depth study of BMAL1." (PMID 40429770, 2025). "Because glucose metabolism in cardiomyocytes takes on greater importance under pathologic conditions including myocardial ischemia and hypertrophy, we next investigated the possibility of compensatory induction of the glycolytic pathway in Bmal1−/− hearts." (PMID 25389966, 2014). "Therefore, from these results, we predicted that alteration of LSG neural activity attributed to changes of these genes by Bmal1 knockdown and thereby prevented ventricular arrhythmias after myocardial ischemia." (PMID 36247430, 2022). "Bmal1 knockdown in the LSG suppresses neural activity and prevents ventricular arrhythmias after myocardial ischemia." (PMID 36247430, 2022). "All these data suggested that Bmal1 knockdown in the LSG significantly stabilized left ventricular electrophysiological properties and reduced myocardial ischemia-induced VAs." (PMID 36247430, 2022). "Thus, in our study, we knocked down the expression of Bmal1 in the LSG to explore its influence on neural activity, and the occurrence of VAs after myocardial ischemia, and elucidate its molecular mechanisms." (PMID 36247430, 2022).
non-small cell lung carcinoma (4 papers, 2023 to 2026). A group of at least three distinct histological types of lung cancer, including non-small cell squamous cell carcinoma, adenocarcinoma, and large cell carcinoma. "This study identifies BMAL1, a core circadian regulator, as a key driver and potential initiator of cisplatin resistance in non-small cell lung cancer (NSCLC) through metabolic and oxidative stress pathways." (PMID 42029117, 2026). "For example, in fibrosarcoma and non-small-cell lung cancer cell lines, autophagy-mediated BMAL1 degradation facilitates EGLN2 expression to destabilize HIF1A which ultimately increases lipid peroxidation." (PMID 37845346, 2023).
skin aging (4 papers, 2022 to 2025). The gradual irreversible changes in structure of skin that occur as a result of the passage of time.. "We for the first time demonstrated that SBG antagonizes REV-ERBα to up-regulate BMAL1 (a skin aging-inhibiting factor) and to protect against skin aging in mice." (PMID 36249807, 2022). "We demonstrated that PLR acts as an antagonist of REV-ERBα and promotes the expression of BMAL1 to protect against skin aging in mice." (PMID 36618934, 2022). "In conclusion, SBG antagonizes REV-ERBα to up-regulate BMAL1 and to protect against skin aging in mice." (PMID 36249807, 2022). "ARNTL, also called BMAL1 has been shown to affect skin aging by regulating circadian rhythms." (PMID 37905958, 2023). "Therefore, we proposed that PLR ameliorates UVB-induced skin aging in mice by increasing skin expression of BMAL1 via antagonism of REV-ERBα and promoting the antioxidant defense." (PMID 36618934, 2022). "Because Bmal1 and its upstream regulator Rev-erbα are involved in skin aging, we wondered whether Bmal1 has a role in protection of skin aging by SBG." (PMID 36249807, 2022). "Therefore, the protective effects of SBG on skin aging can be attributed to enhanced BMAL1 expression." (PMID 36249807, 2022). "Because previous studies have identified BMAL1 as a key regulator of skin aging, we wondered whether PLR can modulate the expression of BMAL1 to alleviate UVB-induced skin aging." (PMID 36618934, 2022). "Taken together, Rev-erbα ablation up-regulated skin BMAL1 and ameliorated skin aging in mice." (PMID 36249807, 2022). "This study has unraveled that SBG promotes BMAL1 expression to protect against skin aging in mice." (PMID 36249807, 2022). "Furthermore, we found that loss of Rev-erbα (a known repressor of Bmal1) up-regulated skin BMAL1 (a clock component and a known anti-aging factor) and ameliorated skin aging in mice." (PMID 36249807, 2022). "More importantly, we have uncovered that SBG protects against skin aging in mice by antagonizing REV-ERBα and increasing skin expression of BMAL1, an aging-inhibiting factor." (PMID 36249807, 2022).
allergic asthma (3 papers, 2022 to 2025). A asthma with a basis in a pathological type I hypersensitivity reaction. "Mice lacking BMAL1 in myeloid cells (BMAL1-LysM−/−) were used to determine the role of BMAL1 in allergic asthma." (PMID 37314017, 2023).
arteriosclerosis (3 papers, 2011 to 2024). A vascular disorder characterized by thickening and hardening of the walls of the arteries. "The LDL cholesterol/HDL cholesterol ratio, a potent marker for risk of arteriosclerosis, in Bmal1 -/- mice was remarkably greater than that in control mice." (PMID 21966465, 2011). "A detailed profile analysis of the cholesterol contents in lipoprotein fractions revealed that the ratio of LDL cholesterol to HDL cholesterol, a potent marker for risk of arteriosclerosis, in Bmal1 -/- mice was significantly higher than that in control mice even under a regular-diet condition." (PMID 21966465, 2011). "This concept is further supported by studies showing that transplantation of aortic grafts from Bmal1 knockout (KO) into littermate control WT mice is accompanied by robust arteriosclerosis and the up-regulation of macrophages in transplanted vessels." (PMID 27168152, 2016).
attention deficit-hyperactivity disorder (3 papers, 2017 to 2025). A disorder characterized by a marked pattern of inattention and/or hyperactivity-impulsivity that is inconsistent with developmental level and clearly interferes with functioning in at least two settings (e.g. at home and at school). "BMAL1 deficiency in dopaminergic neurons induces attention-deficit hyperactivity disorder (ADHD)-like phenotypes, including hyperactivity, impairments in attention and working memory." (PMID 40646562, 2025). "Attention deficit hyperactivity disorder (ADHD) is also strongly associated with disruption of sleep and circadian rhythms, specifically BMAL1 and PER2 rhythms." (PMID 35156088, 2021).
autoimmune disease (3 papers, 2017 to 2025). A disorder resulting from loss of function or tissue destruction of an organ or multiple organs, arising from humoral or cellular immune responses of the individual to their own tissue constituents. "We demonstrate that mice with a targeted deletion of Bmal1 from myeloid cells have significantly enhanced pro-inflammatory and T cell-polarizing cytokine responses, resulting in heightened inflammation and enhanced susceptibility to the induction of autoimmune disease." (PMID 29234010, 2017). "Similar to RORγ, besides being a transcription activator of BMAL1, RORα drives Th17 signature genes and, thus, targeting RORα has beneficial effects in autoimmune diseases." (PMID 40131242, 2025). "The significant finding of this study is that expression of the clock gene Bmal1 and time-of-day in myeloid cells regulates the innate and adaptive immune responses that mediate autoimmune diseases." (PMID 29234010, 2017). "Therefore, we hypothesized that BMAL1 expression and the molecular clock in myeloid cells might be important in CNS autoimmune disease through modulation of innate immunity." (PMID 29234010, 2017).
chronic kidney disease (3 papers, 2022 to 2025). Impairment of the renal function secondary to chronic kidney damage persisting for three or more months. "Presently, research is limited to animal studies, and some debates persist, resulting in insufficient clinical evidence to support circadian rhythm regulation or Bmal1-targeted therapies for acute kidney injury and chronic kidney disease." (PMID 39858471, 2025). "Additionally, we discussed the therapeutic potential and future prospects of Bmal1 in treating both acute kidney injury and chronic kidney disease." (PMID 39858471, 2025). "It has been established that the expression of Bmal1 in the kidneys affects fibrosis and may serve as a therapeutic strategy to mitigate chronic kidney disease and slow its progression." (PMID 39858471, 2025). "Current investigations into the effects of the circadian gene Bmal1 on chronic kidney disease (CKD) primarily focus on directly altering Bmal1 expression to assess its role in chronic kidney injury." (PMID 39858471, 2025).
chronic myeloid leukemia (3 papers, 2015 to 2019). "Decreased expression of PER1/2/3 (and CRY1/2 and BMAL1) has also been observed in the blood of patients with chronic myeloid leukemia (CML) when compared to the blood of healthy individuals." (PMID 33089179, 2019). "Our results suggest that interfering with Sirt1 leads to a partial restoration of BMAL1 oscillation in chronic myeloid leukemia patient samples." (PMID 30210557, 2017). "It has been demonstrated that the expression levels of the human CRY1, CRY2, PER1, PER2, PER3, and BMAL1 genes were down-regulated in both the chronic phase and blast crisis in chronic myeloid leukemia (CML)." (PMID 26253128, 2015).
dementia (3 papers, 2022 to 2025). Loss of intellectual abilities interfering with an individual's social and occupational functions. "The suprachiasmatic nucleus degenerates, and melatonin is not secreted rhythmically due to changes in the expression of circadian clock genes, such as Bmal1, inducing accumulation of amyloid plaques that cause dementia." (PMID 35409846, 2022). "Furthermore, integrating genetic and epigenetic analyses—such as the role of circadian regulation genes (e.g., CLOCK and BMAL1) or APOE variations—could elucidate individual variability in sleep-dementia pathways and support the development of personalized interventions." (PMID 40214959, 2025).